INS (insulin)
Diseases named in the same sentence as INS in open-access papers (continued):
Sharing a sentence is not in itself a finding about the gene and the disease.
diabetes (continued). "A systematic review of evidence on the pathophysiology of thisphenotype and further studies on adequate sample size to identify potential reasonsto ketosis at diabetes onset and the duration of insulin requirement are required toprovide evidence for its management." (PMID 31673335, 2019). "For example, of 26 inflammatory biomarkers evaluated in a longitudinal analysis of ~1000 subjects from the Rotterdam Study, plasma IL-13 levels were inversely associated with progression from normoglycemia to pre-diabetes, incident T2DM, and initiation of insulin therapy." (PMID 30755607, 2019). "Type 1 diabetes mellitus causes insulin dependence due to the pancreas producing very little to no insulin, thereby requiring an exogenous supply of insulin." (PMID 31781665, 2019). "Diabetes mellitus is a heterogeneous group of disorders characterized by persistent hyperglycemia with carbohydrate, lipid, and protein metabolism resulting from defects in insulin secretion and/or insulin action." (PMID 31665087, 2019). "Similar researches have found that there is a negative correlation between SHBG with insulin levels, insulin resistance, and diabetes risk, and researchers believe that low serum SHBG is an independent risk factor for type 2 diabetes." (PMID 31752806, 2019). "Two cases of diabetes were also controlled with insulin therapy." (PMID 31182061, 2019). "Furthermore, 35% of the participants were on insulin therapy, while 81.7% had been exposed to diabetes education and many (79.2%) owned a glucometer." (PMID 30918673, 2019). "By integrating glucose-triggered drug delivery with minimal patient intervention and improved diabetic life quality, glucose-sensitive drug delivery systems may prove valuable in diabetes therapy and replace frequent insulin injection." (PMID 30893913, 2019). "Chronic heavy drinkers who were non-carriers of the INSR AACT haplotype had a higher incidence of diabetes, indicated by decreased disposition index reflecting β-cell function and composite insulin sensitivity, compared with carriers of the AACT haplotype or never-drinkers." (PMID 31882596, 2019). "Therefore, the recombinant GM4-ΔTS-PGK1-CCT-insulin strain can be used as a producer of exogenous insulin for the treatment of diabetes, and has a significant hypoglycemic effect." (PMID 30744426, 2019). "Tobacco product contains nicotine which has established evidence in insulin secretion and action, hence it justifies the association of the current user and non-user of tobacco products with diabetes-tuberculosis comorbidity." (PMID 31752802, 2019). "In conclusion, cassia seed extract could obviously improve the insulin resistance of diabetes rats and enhance the insulin sensitivity of the skeletal muscle." (PMID 31890042, 2019). "In this study, we found that defective insulin signaling also existed in pancreatic islets and may play a critical role in the development and progression of diabetes in both Akita and db/db mice." (PMID 31311313, 2019). "Type 2 diabetes mellitus (T2DM) is the more common type of diabetes where peripheral insulin resistance and compensatory increased insulin secretion may accelerate the decrease in pancreatic islet secretory function, eventually leading to insulin deficiency." (PMID 30800211, 2019). "In particular, obesity induces insulin resistance, which is a preliminary stage of diabetes, through various mechanisms, including insulin overproduction due to excessive nutritional intake, decreased insulin receptor (IR) function, and/or deficit in the intracellular signaling system." (PMID 31311133, 2019). "Exercise may be a simple, yet effective intervention to supplement insulin therapy and minimize risks of birth defects in mothers with diabetes." (PMID 31211496, 2019).
diabetes (continued). "During the development of diabetes, the cells of the body cannot metabolize sugar properly due to deficient action of insulin on target tissues resulting from insensitivity or lack of insulin (a peptide hormone that regulates blood glucose)." (PMID 31575072, 2019). "When analyzing PHQ-2 score by diabetes type and insulin usage, participants using insulin showed a statistically significant decline in PHQ-2 score (1.03 to 0.19; P=.01), while type 1, type 2, and participants not using insulin saw a nonstatistically significant improvement in scores." (PMID 31593545, 2019). "Surprisingly, one patient with low TBSA (4%–5%) who presented diabetes mellitus with hyperglycemia and was poorly controllable by high-dose insulin was successfully treated with voriconazole, which is known to lack meaningful in vitro activity against Mucorales." (PMID 30901836, 2019). "In diabetes, the early-phase insulin secretion is deficient or absent, whereas the second-phase insulin secretion is delayed and exaggerated." (PMID 30728346, 2019). "Subsequent studies focused on autoimmune disease and showed that murine T-cells expressing the B2M/CD3-zeta protein and presenting insulin peptides could reduce progression of diabetes in mice by targeting insulin-specific diabetogenic T-cells." (PMID 31340822, 2019). "However, a recently-published randomized control trial found no impact of an isocaloric diet consisting of PP when provided as 30% of energy intake compared to AP intake on insulin sensitivity in a population with type 2 diabetes mellitus (T2DM)." (PMID 31514469, 2019). "This suggests that flavonoids may have a double function, either as an insulin-secretagogue or as an insulin-mimetic agent, and thus considered a new approach in diabetes treatment." (PMID 31658729, 2019). "Hypoglycemia is a common problem in children with type 1 diabetes mellitus (T1DM) because of the challenges presented by insulin dosing, variable eating patterns, erratic activity, and the limited ability of small children to detect early signs of hypoglycemia." (PMID 31093506, 2019). "Thus, it has been assumed that IGF1R are mainly responsible for the acceleration of arterial intima hyperplasia in diabetes and insulin-resistant states." (PMID 31562314, 2019). "As an example, youth mentioned that a diabetes care team member who could see the kinds of food they ate on their social media account might be able to provide better recommendations regarding insulin dose adjustments and nutrition recommendations." (PMID 31199310, 2019). "Another factor may be that with increased fitness people with diabetes are able to exercise at a greater workload, which may contribute to increased insulin sensitivity and greater glucose utilization." (PMID 31161377, 2019). "Furthermore, a recent study by our group documented a decrease in BMI, WC, HbA1c and an increase in HDL-C in patients treated with DR-HC for 36 months, showing a significant improvement in insulin secretion and sensitivity, even in patients with pre-diabetes." (PMID 31252397, 2019). "Peptides, as therapeutic agents, possess many advantages, such as small size, ease of large-scale synthesis and good biocompatibility Some of them, like insulin for the treatment of diabetes and aflibercept for the treatment of macular degeneration, are currently used in daily clinical practice." (PMID 31762939, 2019). "This provides evidence that longer-term recognition memory deficits occur in diabetic rats and that these deficits are diabetes-associated, can be ameliorated by insulin treatment and are therefore not an indirect effect of STZ." (PMID 31451429, 2019). "The insulin-loaded nanogels with prolonged and stable blood glucose reduction effect may have potential applications for diabetes treatment." (PMID 30893913, 2019).
diabetes (continued). "Another important aspect is whether the beneficial effects of GLP-1 RA and SGLT-2 inhibitors are present in people without established CVD, early in the course of dysglycemia, e. g., the insulin-resistant state and in pre-diabetes." (PMID 30805659, 2019). "Closed‐loop technology may be a feasible option to reduce the burden of glucose management for people with diabetes who require insulin towards the end of life." (PMID 31002426, 2019). "The PLRM using data from the day of ARDS diagnosis found that DAD (OR 2.296 [1.228–4.294]; p < 0.001), diabetes mellitus requiring insulin (OR 0.081 [0.009–0.710]; p = 0.023) and respiratory rate (OR 1.045 [1.001–1.091; p = 0.046] were independently associated with mortality." (PMID 31212621, 2019). "Patients of non-EuroCaucasian origin had a more severe diabetes phenotype than EuroCaucasians, as shown by higher HbA1c values (9.6% vs. 6.6%, p = 0.0001); more frequent symptoms of diabetes (44% vs. 10%, p < 10−4); and requirement for insulin therapy at diabetes diagnosis (42% vs. 13%, p = 0.0002)." (PMID 31291970, 2019). "Additionally, ~ 20% of hospitalized people with insulin‐treated diabetes experience one or more episodes of hypoglycaemia, with 8% of episodes classed as severe." (PMID 31441089, 2019). "Of those who were currently using diabetes apps for their self-management, 120 (21.9%) of respondents with type 1 diabetes reported using their app for calculating insulin doses, of which 29 (25%) mentioned that they had erroneous results in calculating insulin doses with these apps." (PMID 30881349, 2019). "Age and male sex were associated with gastric cancer mortality, but diabetes type, insulin use, and smoking were not." (PMID 31518336, 2019). "Lead may possibly contribute to diabetes since Pb is a pro-oxidant, and oxidative stress alters and reduces insulin signaling." (PMID 31685843, 2019). "The molecular basis for the involvement of magnesium in the pathogenesis of diabetes may lie in its role as a co-factor in several pathways, including glucose transport and insulin sensitivity and secretion." (PMID 31604444, 2019). "The frequent continuation of other diabetes medications while initiating insulin therapy underscores the need for further research into diabetes treatment during the insulin transition to inform evidence-based guidelines that promote optimal management during this critical transition in care." (PMID 30759121, 2019). "On the back of a napkin, John and Duane drew models of a disposable, cost-effective, mechanical insulin delivery device about the size of matchbox that could be discreetly worn directly on the body by people with diabetes." (PMID 30239214, 2019). "At the age of 19 years, he skipped insulin injections and developed ketoacidosis." (PMID 30968599, 2019). "RSG is mainly used as an insulin sensitizer for the treatment of diabetes." (PMID 31217747, 2019). "Therefore, restoration of insulin-producing β-cells would be a logical strategy for the treatment of both forms of diabetes." (PMID 31839754, 2019). "Furthermore, PAX4 is involved in the differentiation of insulin-producing β- and δ-cells of the pancreas, and certain mutations in PAX4 can lead to the development of severe diabetes mellitus." (PMID 31216190, 2019). "Our results also showed that insulin treatment could partially reverse the deleterious effects of diabetes on offspring follicle development." (PMID 30973884, 2019). "In diabetes, insulin and adiposity can influence PIV over time." (PMID 31333501, 2019). "Catalpol has demonstrated potential glucose-lowering effect in experimental type-1 and type-2 diabetes mellitus; these effects may be related to improved glucose utilization in insulin-sensitive tissues and improved mitochondrial biogenesis/function." (PMID 31878316, 2019). "Moreover, in insulin resistant subjects with diabetes, despite elevated expression of sXBP1, the SDF2L1/sXBP1 ratio and the HSPA5/sXBP1 ratio were significantly lower." (PMID 30814508, 2019).
diabetes (continued). "Despite such initiatives, insulin errors remain a problem, with evidence from the 2017 National Diabetes Inpatient Audit suggesting that almost half of patients treated with insulin experience a medication error related to their insulin (49%), an increase compared to previous years (46% in 2016)." (PMID 30704103, 2019). "Diabetes mellitus (DM) is a complex metabolic disorder resulting from immune-mediated destruction of insulin-producing cells in the islets of Langerhans (type 1 diabetes mellitus—T1D) or from the combination of insulin resistance and relative insulin deficiency (type 2 diabetes mellitus—T2D)." (PMID 30804929, 2019). "Many microRNAs, such as let-7, miR-223, miR-29, miR-103, and miR-107, are known to regulate metabolic disorders (including diabetes) through various molecular pathways, such as modulation of lipid or glucose metabolism, liver gluconeogenesis, insulin secretion, and autophagy." (PMID 31398847, 2019). "Treatment with SGLT2 inhibitors in patients with diabetes could provide better glycaemic control and insulin sensitivity and reduce arterial blood pressure, arterial stiffness, body weight, and visceral fat27–30." (PMID 31653956, 2019). "Insulin and IGF-1 actions in vascular smooth muscle cells (VSMC) are associated with accelerated arterial intima hyperplasia and restenosis after angioplasty, especially in diabetes." (PMID 31562314, 2019). "The mean (SD) duration of diabetes was 12.0 (4.8) years, mean (SD) HbA1c was 8.4% (1.5%), and 20 of 33 participants (61%) were using continuous subcutaneous insulin infusion (insulin pump) as their means for insulin administration." (PMID 31298715, 2019). "Importantly, oxidative stress can regulate insulin secretion in different ways and accelerate the development of diabetes mellitus." (PMID 31013790, 2019). "Importantly, as diabetes progresses, KATP-GOF mice demonstrate a marked loss of insulin content, a typical secondary consequence of glucotoxicity." (PMID 31061431, 2019). "According to the American Diabetes Association (ADA), diabetes mellitus is a metabolic disease characterized by severe hyperglycemia due to defects in insulin secretion or the lack of proper action of this hormone in the target tissues." (PMID 31915708, 2019). "Diabetes is divided into two types: type 1, in which the beta-cells of the pancreas are damaged and affected people need external administration of insulin; and type 2, which is peripheral insulin resistance, and is present in 85% of the patients with diabetes." (PMID 31024426, 2019). "When insulin secretion and synthesis in diabetes patients are reduced, and/or insulin resistance sets in, alterations of blood glucose metabolism follow, which in turn cause the acceleration of fat decomposition and slow down fat utilization rate, leading to altered lipid metabolism." (PMID 30936849, 2019). "Specifically, patients initiating dapagliflozin vs those initiating GLP‐1RA were slightly younger and more often male, with a longer diabetes duration, lower BMI, higher fasting plasma glucose and HbA1c, better renal function, and more frequently were using metformin and insulin." (PMID 30985052, 2019). "Previous studies have demonstrated that the role of FFAs in human health is sensed and regulated by FFA receptors, and these FFA receptors play an essential role in lipid and energy metabolism, insulin resistance, fat accumulation, and even pathogenesis of obesity and diabetes." (PMID 31360149, 2019). "Notably, we found that the greater risk of CV death was due to a higher rate of sudden death rather than pump failure death in insulin‐treated compared to non‐insulin‐treated patients with diabetes." (PMID 31271255, 2019).
diabetes (continued). "In the present study, the omentin gene expression was examined in adipose tissues of T1D and T2D mice models that were induced by higher and lower doses of STZ with normal pellet and HFD diet for the investigation of the effects of fat mass on insulin metabolism in different types of diabetes." (PMID 31428203, 2019). "Stem cell-derived insulin-secreting cells were recently suggested as a novel therapy for diabetes." (PMID 31018536, 2019). "Diabetes is a chronic disease characterized by disorders in insulin secretion." (PMID 30823497, 2019). "I.e. insulin or metformin used at home indicates that the patient has diabetes." (PMID 31039162, 2019). "The implication of the findings of the present systematic review for the clinical practice is the possibility of safely choosing the drug for the treatment of pregnant women with diabetes, in which case it is possible to use both human insulin and insulin analogs." (PMID 30786308, 2019). "We found that 3-year changes of fasting insulin and IR indices are strong risk factors for developing hypertension among normotensive healthy adults without known diabetes, independent of large set of covariates and BMI changes." (PMID 31728151, 2019). "Insulin might also contribute to the restoration of impaired EDH in diabetes independently of its glucose-lowering properties." (PMID 31370156, 2019). "In fact, most of the individuals with diabetes were burdened by engaging in dietary self-management compared to engaging in other types of diabetes self-management like exercise, insulin injection, self-monitoring of blood sugar, and taking oral antihypertensive agents." (PMID 31731588, 2019). "However, when insulin secretion is inadequate to meet the metabolic demand, blood glucose levels remain high, resulting in diabetes." (PMID 31382473, 2019). "While diabetes is an established risk factor for the development of heart failure after myocardial infarction, the role of insulin resistance in post-infarction LV remodeling in non-diabetic patients is less understood." (PMID 31391045, 2019). "Closed‐loop insulin delivery offers a novel approach to glucose management for people with diabetes who require insulin towards the end of life, and may be safer and less burdensome than standard insulin therapy." (PMID 31002426, 2019). "Indeed, a recent study suggests that the lipid-lowering effect of insulin can improve heart function in elderly individuals with diabetes." (PMID 31031709, 2019). "This route opens a window in order to aid the development of enteral nutrition formulas, such as the recent study published by Mesejo and colleagues which developed a high-protein diabetes-specific formula that reduces insulin needs and improves glycemic control." (PMID 31466386, 2019). "Diabetes mellitus (DM) has been defined as a group of disorders characterized not only by hyperglycemia but also by altered insulin action or secretion, altered metabolism of proteins, carbohydrates, and lipids, and the increased risk of vascular complications." (PMID 31308875, 2019). "The reasons for the defective regression in patients with diabetes are unclear and whether this is due to defective insulin signaling, hyperglycemia or aggravated hyperlipidemia is subject of ongoing research." (PMID 31784656, 2019). "This may also help ameliorate the substantially worse health‐related quality of life in patients with insulin‐treated diabetes." (PMID 31271255, 2019). "The exact mechanism whereby relatively low BMI at college age increases the risk of diabetes is unclear, but recent data demonstrated that in non-obese Asians, this risk is elevated not only by impaired insulin secretion, but also by insulin resistance." (PMID 30677099, 2019). "As such, islet transplantation has emerged as a promising treatment for diabetes as it overcomes the deficient or inadequate insulin secretion in the most natural way and without any of the negative side-effects seen with exogenous insulin therapy." (PMID 30850640, 2019).